IL6 (interleukin 6)
Diseases named in the same sentence as IL6 in open-access papers (continued):
Sharing a sentence is not in itself a finding about the gene and the disease.
hip fracture (24 papers, 2012 to 2025). Traumatic or pathological injury to the hip in which the continuity of either the femoral head, femoral neck, intertrochanteric or subtrochanteric regions is broken. "Further multivariable analysis showed that three factors including age, low preoperative MMSE scores, and low postoperative plasma IL-6 levels were independent risk factors in POD among older hip fracture patients." (PMID 36482916, 2022). "For example, one study reported the inflammatory cytokines interleukin-6 (IL-6) and tumour necrosis factor-alpha (sTNF-αR1) were associated with depressive symptoms 1 year after hip fracture." (PMID 34627160, 2021). "Several studies have shown that 30-day mortality after a hip fracture is associated with elevated inflammatory cytokines, such as C-reactive protein, interleukin (IL)-6, IL-8, tumor necrosis factor-α, and soluble urokinase plasminogen activating receptor." (PMID 32850880, 2020). "In order to determine if hip fracture surgery was associated with changes in serum cytokine levels, IL-6, TNF-α, IL-1β, and IL-10 levels in blood were quantified 1, 3, and 7 days after hip fracture and surgery (including sham-operated controls)." (PMID 24163505, 2013). "Interestingly, as shown in the ANCOVA model there was a significant association between GDS scores and IL6 levels in hip fracture patients, β = .29, p = .02, ΔR2 = .087, such that those with greater depressive symptoms had higher IL6." (PMID 23876747, 2013). "C-reaction protein, interleukin-6, and tumor necrosis factor-α are all inflammation biomarkers that have been shown to predict mortality events in hip fracture patients." (PMID 36628151, 2022). "We have previously reported that elevated levels of TNFα and IL6 were seen in hip fracture patients with depressive symptoms compared with patients without depressive symptoms and healthy controls." (PMID 25628751, 2014). "On examining cytokine production by activated T cells, a significant increase in TNFα (p = .03) and IL6 (p = .04) production was observed in CD4 T cells from hip fracture patients with depressive symptoms compared to healthy controls." (PMID 25628751, 2014). "This is consistent with findings of a previous study examining cytokine levels in hip fracture patients, according to which older hip fracture patients with high levels of pro-inflammatory cytokines such as IL6 had higher GDS scores." (PMID 23876747, 2013). "In this study, we have reported elevated levels of TNFα and IL6 in hip fracture patients with depressive symptoms compared with patients without depressive symptoms and healthy controls." (PMID 23876747, 2013). "Elevated RPP at admission is a risk factor of POD in elderly patients undergoing hip fracture surgery and the effect of RPP at admission on POD may be partially mediated by preoperative plasma IL-6." (PMID 41229511, 2025). "This study is aimed at examining the differential expression of miR-146a, miR-150, and cytokines (IL-6 and IL-10) between younger and elderly rats suffering from hip fracture and investigating the possible meaning of them in early diagnosis and prognosis of ALI after hip fracture." (PMID 30510490, 2018). "Recently, some inflammatory markers, such as interleukin-6 (IL-6), C-reactive protein (CRP), prognostic nutritional index ratio (PNI), CRP/PNI ratio, and neutrophil-to-lymphocyte ratio (NLR) were found to be independently associated with increased early and long-term mortality after hip fracture." (PMID 33663402, 2021). "Interestingly, a decreased level of IL-6 was found in pre-operative cerebrospinal fluid (CSF) from elderly hip fracture patients, thus, suggesting not only a potential role of the molecular up-taking but also the importance of the anti-inflammatory balance in the brain." (PMID 25368603, 2014). "Particularly, patients with hip fracture have significantly increased serum levels of inflammatory cytokines (e.g., TNF-α, IL-6, IL-10) compared with healthy controls." (PMID 29357879, 2018).
hip fracture (continued). "Transversus abdominis plane block was postulated to attenuate the production of IL-6 in patients of advanced age undergoing laparoscopic rectal cancer surgery, and femoral nerve block reduced the expression of TNF-α in elderly patients with a hip fracture." (PMID 32756520, 2020). "However, the alterations in cardiac glucose and fatty acid transporters following bone fracture were recently demonstrated to be induced by pro-inflammatory mediators such as HMGB1, IL-1β, IL-6 and TNF, all of which have been shown to be elevated following hip fracture in the present study." (PMID 36131923, 2022). "These symptoms were associated with poorer neutrophil superoxide production and a higher cortisol:DHEAS ratio, as well as greater levels of the cytokines IL6 and TNFα and lower IL10, compared to healthy controls and hip fracture patients without depressive symptoms." (PMID 23876747, 2013).
inflammatory skin disease (24 papers, 2017 to 2025). Inflammatory skin disorders covers a broad category that includes many conditions ranging in severity, from mild itching to grave medical health complications These disorders are common in people of all ages and races. "Therefore, regulating the NLRP3 inflammasome and its associated cytokines, including IL-1β, IL-18, and IL-6, is important in preventing inflammatory skin diseases." (PMID 37175425, 2023). "TNF-α plays a central role in the pathogenesis of inflammatory skin disorders by activating endothelial and dermal cells, thereby upregulating downstream mediators such as IL-6 and MMP-9." (PMID 41404493, 2025). "Since IL-24 is involved in the pathogenesis of inflammatory skin diseases and since it is induced by IL-6, we further characterized the effect of R7 on IL-6 and IL-24 expression and secretion." (PMID 40461723, 2025). "UVB radiation can induce inflammatory mediators such as COX-2 and pro-inflammatory cytokines, including TNF-α, IL-6, and IL-1β, which induce the expression of NF-κB, which has been shown in inflammatory skin diseases." (PMID 38275645, 2023). "In humans, matriptase activation was coupled to several inflammatory skin disorders, and matriptase induced IL-6 and IL-8 production of endothelial cells via PAR-2-mediated inflammatory signaling." (PMID 33919461, 2021). "The role of IL-6 in the pathogenesis of a host of inflammatory skin diseases has been well documented." (PMID 31781680, 2019). "Additional studies regarding the effect of UVB-induced IL-22 production and IL-22Rα expression on the production of IL-1α, IL-6, and IL-18 will provide a basis for further understanding the role of IL-22 in the control of inflammatory skin disease." (PMID 28558005, 2017). "Additionally, TNF-α stimulates the release of other proinflammatory cytokines such as interleukin-6 (IL-6) and interleukin-8 (IL-8), contributing to inflammatory skin disease." (PMID 40364386, 2025). "IL-6 signalling is related to inflammatory infiltration by controlling the expressions of inflammatory chemokines and adhesion molecules and has been reported to promote keratinocyte proliferation and lead to inflammatory skin disorders." (PMID 37047066, 2023). "Also, the evaluation of the expression of IL-6 in other canine inflammatory skin diseases could elucidate whether the observed IL-6 expression pattern is unique to CHRs." (PMID 39194759, 2024). "In addition, IL-6 plays a crucial role in various inflammatory skin diseases." (PMID 39588538, 2024). "Given that IL-1α and IL-6 are involved in the pathogenesis of skin diseases caused by proliferation of keratinocytes, IL-22-dependent regulation of UVB-induced IL-1α, IL-6, and IL-18 production may be important in the mechanism of inflammatory skin diseases." (PMID 28558005, 2017). "In another study on the effects of topical DP treatment on inflammatory skin disease, DP treatment reduced lesion size and mRNA expression levels of the inflammatory cytokines, TNF-α, IL-6, and IL-8." (PMID 36641447, 2023). "AS inhibits the production of NO in a concentration-dependent manner and inhibits inflammatory cytokines (IL-6, TNF-α) in LPS-stimulated mouse macrophage RAW264.7 cells, suggesting that AS has potential for the treatment and prevention of inflammatory skin diseases." (PMID 36616208, 2022). "When the epidermal barrier of the skin is damaged by physical or chemical stimuli, many cytokines (IL-1β, IL-6, TNF-α, IL-5, and TSLP) and chemokines (MCP-1, RNATES, TARC, MDC, CXCL8, and CXCL10) are expressed in stimulated keratinocytes to promote the progression of inflammatory skin diseases." (PMID 36670888, 2022).
osteomyelitis (24 papers, 2010 to 2026). An acute or chronic inflammation of the bone and its structures due to infection with pyogenic bacteria. "Pro-inflammatory cytokines such as IL1B and IL-6 are considered to be significant risk factors for osteomyelitis." (PMID 37904457, 2023). "Increased serum levels of IL-6 found in patients with active osteomyelitis play a causative role in decreased peripheral blood neutrophil apoptosis." (PMID 20370895, 2010). "Genetic studies in osteomyelitis have suggested that certain polymorphisms in genes associated with immune modulation, such as those encoding cytokines (e.g., IL-1, IL-6, TNF-α), may affect disease susceptibility, progression, and response to treatment." (PMID 40142310, 2025). "Additionally, the study found that individuals with the homozygote for the C allele of IL-6 rs1800795 C allele were at an increased risk of developing osteomyelitis." (PMID 39301021, 2024). "Moreover, some studies have demonstrated local production of IL-6 at bacterial infection sites in human osteomyelitis associated with S. aureus, as well as in a murine model." (PMID 39208074, 2024). "Similarly, the application of precise inhibitors that specifically target genetic variations in the IL-6 gene, notably the rs1800795 polymorphism, effectively reduces inflammation and arrests the progression of osteomyelitis and PJI." (PMID 39301021, 2024). "The study is the first to investigate the clinical significance of inflammatory biomarkers (NLR, PLR, MLR and PMR), the SII, and IL-6 in a well-established rabbit model of orthopedic infections to evaluate the progression of chronic osteomyelitis development." (PMID 39208074, 2024). "Recent studies have uncovered a correlation between the development of osteomyelitis and specific SNPs in IL-4 (rs2243248, rs2243250, and rs2070874) as well as SNPs in IL-6 (rs1800795, rs1800796)." (PMID 39301021, 2024). "It has been definitively established that IL-4 and IL-6 play a direct role in bone resorption and the regulation of osteoclast activity in chronic osteomyelitis." (PMID 39301021, 2024). "Interleukin-6 plays a key role in promoting osteomyelitis through signalling receptor protein gp130 binding." (PMID 38310564, 2024). "In the case of osteomyelitis, key SNPs within genes such as IL-1β (including rs1143634 and rs16944), IL-6 (e.g., rs1800795), VDR, and TNF-α are instrumental in evaluating susceptibility." (PMID 39301021, 2024). "NLR, PLR and SII, complemented by IL-6 can be used as fairly accurate biomarkers for the diagnosis of osteomyelitis." (PMID 39208074, 2024). "While IL-6 is recognized to be produced throughout the course of osteomyelitis, and has been found to be similarly useful in diagnosis of chronic osteomyelitis as C-reactive protein (CRP) and erythrocyte sedimentation rate (ESR)." (PMID 36726643, 2022). "In patients with osteomyelitis, IL6 was correlated with longer neutrophil survival apart from other cytokines; this anti-apoptotic effect was blocked using anti-IL6 antibodies and reversed with anti-IL630." (PMID 33958640, 2021). "Several works have demonstrated that Staphylococcus aureus infected osteoblasts in osteomyelitis induce IL-6 and IL-12 secretion." (PMID 23304158, 2012). "In this respect, several preclinical and clinical observations indicate that osteomyelitis is accompanied by alterations in the local and (sometimes) systemic levels of both pro-inflammatory (e.g., IL-6, IL-1α, TNF-α, IL-1β) and anti-inflammatory (e.g., TGF-β1) cytokines." (PMID 36483565, 2022). "Previous work has shown that IL-1β and IL-6 production is increased during osteomyelitis." (PMID 34484165, 2021). "Cytokine IL-6 inhibits apoptosis of PMN in patients with osteomyelitis and could inhibit the natural apoptosis of endogenous neutrophils." (PMID 32408873, 2020). "Inflammatory markers including IL-6 do not allow reliably diagnosing implant-associated osteomyelitis in patients with nonunion." (PMID 29130050, 2017).
osteomyelitis (continued). "Also, synovial IL-6 has been documented to detect PJI in a cohort of THA and TKA patients, and the rs1800796 polymorphism in the IL-6 gene has been associated with post-traumatic osteomyelitis." (PMID 38790226, 2024). "Inflammatory markers, such as interleukin-6 (IL-6), tumor necrosis factor-alpha (TNF-α), procalcitonin (PCT), and C-reactive protein (CRP), serve as pivotal indicators in assessing the severity of osteomyelitis." (PMID 40956854, 2025). "Similar to the clinical osteomyelitis S. aureus strain UAMS-1, the USA300 methicillin-resistant strains, HFH 29568 and TCH 1516, stimulated a significant production of IL-6 and IFN-β by primary murine and human osteoblasts." (PMID 40135931, 2025). "The findings suggest potential linkages between SNPs in genes such as IL-1, IL-6, IFN-γ, TNF-α, VDR, tPA, CTSG, COX-2, MMP1, SLC11A1, Bax, NOS2, and NLRP3 with the development of osteomyelitis." (PMID 39301021, 2024). "Proinflammatory cytokines such as interleukin 1 (IL-1), interleukin 6 (IL-6), or tumor necrosis factor alpha (TNF-α), are produced in S. aureus-induced osteomyelitis." (PMID 31832182, 2019). "Current research has amassed increasing evidence suggesting that SNPs in various genes, including IL-1, IL-6, IFN-γ, TNF-α, VDR, tPA, CTSG, COX-2, MMP1, SLC11A1, Bax, NOS2, and NLRP3, may contribute to the development of osteomyelitis." (PMID 39301021, 2024). "Among them, IL1B, IL-6, IL8, and MMPs may be involved in the common pathogenesis of silver DFU and osteomyelitis." (PMID 37904457, 2023). "Osteomyelitis was an essential part of bone infection disease and characterized by a severe inflammatory reaction that contributed to bone destruction due to the release of pro-inflammatory cytokines (TNF-α, IL-1β and IL-6) from many bacterial." (PMID 32527985, 2020). "Moreover, the increased serum and extracellular levels of IL-8 and IL-6 have been reported in acute pyelonephritis, vesicoureteral reflux, pulmonary infections, osteomyelitis, and both hematologic and non-hematologic malignancies." (PMID 33906316, 2021).
aortic aneurysm (23 papers, 2009 to 2024). A ruptured aneurysm located in the wall of the proximal portion of the descending aorta proceeding from the arch of the aorta. "Evidence suggests that interleukin-6 (IL6) signaling is causally associated with aortic aneurysm independently of the effect of C-reactive protein (CRP)." (PMID 34168680, 2021). "Neutrophils contribute to the formation of aortic aneurysms by secreting neutrophil extracellular traps and the inflammatory molecule IL-6." (PMID 38627614, 2024). "It has been shown that IL-6 recruits CCR2-positive monocytes which serve to amplify the inflammatory cascade, and IL-6 signaling contributes to Angiotensin II-induced aortic aneurysm." (PMID 33175881, 2020). "There is growing number of evidence that suggests aortic aneurysms secrete IL-6 into the circulation." (PMID 28243294, 2016). "Previous studies suggested that leukocyte-fibroblast interactions in the aortic adventitia potentiate IL-6 production-mediated vascular inflammation, leading to aortic aneurysm and dissection." (PMID 25876091, 2015). "IL-6 is also an inflammatory cytokine that plays an important role in aortic aneurysms." (PMID 36195877, 2022). "In addition to IL-6, IL-10 also played an important role in promoting the development of aortic aneurysm." (PMID 32509885, 2020). "The theory was based on the finding that mural thrombus of an aortic aneurysm contains high amounts of IL-6 and that manipulations with endovascular instruments inside the mural thrombus might release IL-6." (PMID 26166953, 2015). "It has also been noted that IL-6 is secreted at high levels in human aortic aneurysm disease." (PMID 24586754, 2014). "In addition to the systemic inflammatory response to surgical insults, the direct release of IL-6 from aortic aneurysm might contribute to the increase in IL-6 after AAA surgery." (PMID 25960882, 2014). "When macrophages infiltrate the aortic aneurysm wall, they express many inflammatory factors that can promote VSMC-apoptosis, such as interleukin 6 (IL-6), tumor necrosis factor-α (TNF-α), and monocyte chemotaxis protein-1 (MCP-1)." (PMID 37007957, 2023). "Cytokines, such as IL- 1β, IL-6, IFN-γ, or TNF-α have been reported to have higher concentrations in the peripheral blood of patients with aortic aneurysm." (PMID 36148051, 2022). "Initially we confirmed the up-regulation of Il6, Ccl4, Ccl8 and MMP2 within aortic aneurysms using real time PCR." (PMID 19580648, 2009). "In addition, genetic deletion of the MCP-1 receptor C–C motif chemokine receptor 2 (CCR2), IL-6, or MMP-9 ameliorated aortic aneurysm pathogenesis." (PMID 29296021, 2018).